LEP (leptin)
Diseases named in the same sentence as LEP in open-access papers (continued):
Sharing a sentence is not in itself a finding about the gene and the disease.
Obesity (continued). "Leptin is an appetite-regulating hormone, and its deficiency leads to polyphagia, resulting in obesity and diabetes." (PMID 32374776, 2020). "Leptin is a hormone whose levels are directly associated with obesity, myocardial infarction, and hypertension." (PMID 32566092, 2020). "Meanwhile, it has been shown that obesity-associated activation of the hypothalamic NF-κB/IKK-β pathway also mediates leptin functions in the CNS." (PMID 32760236, 2020). "Additional investigations further indicate a positive correlation between leptin and increased cardiometabolic risk, including obesity and hypertension, during adolescence." (PMID 33114326, 2020). "Leptin resistance or leptin signaling deficiency results in the risk increase of cardiac dysfunction and heart failure, which is a leading cause of obesity- and T2DM-related morbidity and mortality." (PMID 32655492, 2020). "The increased TNF-α level is related to the combined effect of obesity and diabetes while increased leptin level is caused by obesity unescorted by diabetes." (PMID 32089876, 2020). "Whereas, adipose eosinophils and IL-4 expression were reduced in mice fed HFD or in mice with genetic obesity secondary to leptin deficiency, and there was an inverse relationship between adipose eosinophil numbers and mouse weight." (PMID 32585823, 2020). "The genetic models of obesity such as the leptin deficient ob/ob mice and leptin receptor-deficient obese db/db mice have increased susceptibility to H1N1 virus infection." (PMID 33123087, 2020). "Leptin SNPrs2167270 G>A study confirmed that, it is highly associated with obesity, since the leptin resistance is the prime characteristic or main feature of the obesity." (PMID 32544194, 2020). "Many of the pathogenic mutations that cause severe early onset obesity affect genes and proteins in the leptin-melanocortin pathways (e.g., LEP, LEPR, POMC, PCSK1, and MC4R)." (PMID 32692746, 2020). "In humans, obesity is associated with an increase in leptin concentrations, suggesting that leptin signaling is impaired." (PMID 32085628, 2020). "We were surprised to find that serotonin was greatly associated with leptin as an obesity-related hormone (R2 of 0.648)." (PMID 33312720, 2020). "In fact, a recent review features several studies that support the notion that a reduction in leptin signalling in the context of obesity is associated with weight loss and metabolic improvements." (PMID 33292104, 2020). "In fact, diet-induced obesity, wherein circulating leptin is increased, yielded the same predisposition to hepatic metastasis as deficiency of the adipokine in ob/ob mice." (PMID 32879136, 2020). "The author concluded that perhaps leptin level is independently associated with high BMI and obesity which is well known to be related with cardiovascular diseases." (PMID 33489600, 2020). "Their obesity-associated markers, semen parameters, and serum reproductive hormones, lipids and leptin were detected." (PMID 32993674, 2020). "The expression of adipokines including leptin, adiponectin, and resistin is dysregulated in obesity and closely associated with secondary metabolic diseases." (PMID 32586265, 2020). "Here, we used leptin-deficient (ob/ob) mice as an animal model for over-feeding to study the effect of AC on obesity." (PMID 32164196, 2020). "Obesity has been associated with frailty (Blaum, Xue, Michelon, Semba, & Fried, 2005), and earlier studies also have shown higher levels of leptin to be associated with frailty (Lana, Valdés‐Bécares, Buño, Rodríguez‐Artalejo, & Lopez‐Garcia, 2017)." (PMID 32762010, 2020). "An abnormally high level of leptin (hyperleptinemia) plays a role in polygenic obesity, while low leptin (hypoleptinemia) is associated with weight loss from an obese state." (PMID 32987813, 2020). "Overall, it is clear that leptin plays a critical role in obesity-associated inflammation by promoting pro-inflammatory immune phenotypes." (PMID 33584724, 2020).
Obesity (continued). "An early report demonstrated a cross-sectional association between serum leptin and obesity expressed as percentage body fat." (PMID 32987813, 2020). "Leptin deficiency is a result of a genetic mutation predisposing subjects to severe obesity, while leptin resistance is linked to dietary obesity." (PMID 32585823, 2020). "Obesity is associated with both the impaired signaling of the adipokine leptin and the occurrence of sleep-disordered breathing." (PMID 32698380, 2020). "Leptin is a hormone mainly secreted by adipocytes, it is involved in the control of food intake and its increased levels are associated to obesity." (PMID 33066277, 2020). "In contrast, alleviating ER stress by treating obese animals with chemical chaperones, like tauroursodeoxycholic acid (TUDCA) or 4-phenylbutyrate (4-PBA), increases leptin sensitivity and attenuates the risk of obesity." (PMID 33071984, 2020). "Deletion of STAT5 has been shown to cause leptin resistance, hyperphagia, and obesity, contributing to leptin-dependent regulation of energy balance and body weight." (PMID 33334030, 2020). "Studies have observed that obesity causes high levels of leptin, which acts as a pro-inflammatory cytokine and amplifies the process of insulin resistance." (PMID 33489589, 2020). "Numerous differences in gene expression related to leptin deficiency and obesity existed between WT and ob/ob mice." (PMID 32346034, 2020). "Leptin-mediated aldosterone production is considered a novel mechanism of obesity-associated endothelial dysfunction and cardiac fibrosis, which impair myocardial relaxation and thereby contribute to cardiovascular disease." (PMID 32655492, 2020). "Obesity-associated asthma probably develops from a systemic inflammation originating in fatty tissue that is associated with an imbalance of leptin and adiponectin." (PMID 33134805, 2020). "In line with these notions, we observed that the Myd88ΔGFAP mice displayed anti-obesity phenotype in association with improved responsiveness to leptin after long-term HFD feeding." (PMID 32560726, 2020). "So far, there have been limited studies about the relationship between obesity-associated markers and leptin concentration male infertile population." (PMID 32993674, 2020). "A high content of liver hydroxyproline (originating mostly from collagen) was also observed in obese leptin‐deficient (ob/ob) mice, in both obesity and NASH mouse models." (PMID 33324348, 2020). "This rare monogenic form of obesity is largely caused by high-risk genetic variations involved in the control of appetite and energy maintenance along the leptin-melanocortin pathway." (PMID 32594318, 2020). "Leptin forms a link between obesity and cancer: obesity is associated with the onset of breast cancer and the development of drug resistance; however, little is known about how obesity contributes to the metastasis." (PMID 33213024, 2020). "On the other hand, high blood leptin can be a risk factor for cardiovascular diseases independently of obesity." (PMID 33114326, 2020). "Increased adipokine leptin secretion in inflammed adipose tissue is associated with decreased energy expenditure, dyslipidaemia, obesity, and IR." (PMID 33204675, 2020). "Leptin inhibits the hypothalamic stimuli for food intake and therefore is highly suspected to be a risk factor for obesity and insulin resistance when deregulated." (PMID 31947745, 2020). "Obesity elevates circulating leptin concentrations (i.e., hyperleptinemia), which in turn causes leptin resistance of the hypothalamus and promotes further weight gain." (PMID 32260528, 2020). "For example, a prospective cohort study of 748 middle-aged white adults reported that baseline leptin levels accurately predicted the future risk of developing MetS and obesity." (PMID 32397260, 2020). "Leptin is not only increased after high fat intake and associated with obesity, but also connected with obesity-linked mucosal intestinal inflammation." (PMID 32295104, 2020).
Obesity (continued). "The converse case of circadian disruption in models of metabolic disease is also observed: the loss of feeding rhythms precedes the development of obesity in leptin deficient ob/ob mice and in diet-induced obesity models." (PMID 32363197, 2020). "Leptin-deficient mice not only develop extreme obesity and other components of the metabolic syndrome but also show decreased brain weight and cortical volumes." (PMID 32547431, 2020). "Leptin deficient (ob/ob) or leptin receptor-deficient (db/db) murine models display obesity and transient diabetes." (PMID 32816039, 2020). "The polymorphism of the leptin gene promoter region is recognized to have an impact on leptin secretion, hence, to be associated with body weight gain and obesity." (PMID 32033608, 2020). "Some researchers have pointed out that obesity increases the risk of thyroid autoimmunity, which is related to leptin levels and other known predictors." (PMID 32256575, 2020). "An additional gene of interest in this region is SIGLEC6 that binds the obesity-associated leptin molecule." (PMID 32728162, 2020). "Obesity is accompanied by altered secretions of leptin, ghrelin, GLP-1, PYY, and CCK, which are in turn associated with accelerated weight gain." (PMID 32756479, 2020). "Despite reports of increased IL-17 in obese individuals, mouse models have shown that IL-17 deficiency worsens the effects of diet-induced obesity, accelerates adiposity in mice fed a low-fat diet, and elevates circulating leptin levels." (PMID 32499756, 2020). "We stratified the individuals into four groups to analyze the associations between LEP polymorphisms and leptin levels with respect to sex and obesity status." (PMID 31914480, 2020). "Several genetic variants of POMC and MC4R genes have been associated to human obesity, suggesting that the central melanocortin system is required for the anorexigenic effect of leptin." (PMID 32069871, 2020). "The increase in the adipose tissue associated with obesity is associated with an increase in leptin levels and a decrease in adiponectin levels." (PMID 32111875, 2020). "According to all that, and as previously demonstrated in the literature, leptin deficiency can easily lead to obesity, but obesity-related to leptin metabolism can also be the result of deleterious leptin’s action." (PMID 32033608, 2020). "Obesity, however, is associated with leptin resistance, a state in which elevated circulating leptin and exogenously delivered leptin are both less effective in creating satiety and suppressing food intake." (PMID 32670063, 2020). "Other obesity associated factors such as adipokines and leptin levels have also been investigated but only contradictory data have been retrieved." (PMID 32670496, 2020). "In this section, we will explore the role that leptin plays in mediating the immune response in obesity-associated disease." (PMID 33584724, 2020). "In a study of 294 healthy adolescents (aged 13–16 years) with a broad ranged BMI, an elevation in leptin levels was associated with impaired arterial distensibility, independent of metabolic and inflammatory disturbances associated with obesity." (PMID 32655492, 2020). "Many studies have used high fat-diet induced obese (DIO) mice and leptin-deficient (ob/ob) mice to mimic human obesity." (PMID 32164196, 2020). "The association between obesity, leptin, and androgenetic alopecia (AGA) in males has been investigated by the group of Yang." (PMID 33008429, 2020). "A prospective case-control study in a Romanian population-The Nutrichild Study Correlations between leptin gene polymorphisms 223 A/G, 1019 G/A, 492 G/C, 976 C/A, and anthropometrical and biochemical parameters in children with obesity." (PMID 32673455, 2020). "This inhibits the expression of adiponectin and increases the expression of leptin, resulting in a reduced adiponectin to leptin ratio in obesity-associated adipose tissue." (PMID 33339340, 2020).
Obesity (continued). "While severe obesity due to congenital leptin deficiency is rare, studies in patients before and after treatment with leptin can provide unique insights into the role that leptin plays in metabolic and endocrine function." (PMID 32392278, 2020). "Despite the growing evidence associating obesity and adipokines, particularly leptin and its receptors, with cancer development and progression, it is still a debatable matter in PCa." (PMID 32573960, 2020). "In the current study, we found that adiponectin, leptin, and LA ratio were prospectively associated with MetS risk among Korean adults even after adjusting for obesity, which is one of the most significant risk factors for MetS." (PMID 32397260, 2020). "Through that mechanism, increased systemic leptin levels in diet-induced obesity directly promote obesity-associated inflammation." (PMID 33584724, 2020). "Our present study aimed to evaluate the PNPLA3, leptin and adiponectin genes polymorphism and the irisin, leptin and adiponectin levels as significant specific biomarkers for obesity and insulin resistance in type 2 diabetes mellitus." (PMID 32544194, 2020). "Research into the mechanisms and effects of obesity has relied on both diet- and genetically induced animal obesity models (e.g., leptin or leptin-receptor-deficient mice)." (PMID 32211204, 2020). "Increased leptin has been related to obesity, inflammation, hypoxia, and has been implicated in ROS generation." (PMID 33333910, 2020). "Patients with homozygous LEP mutations show undetectable levels of leptin in the serum, are characterized by severe early-onset obesity and marked hyperphagia, and develop glucose intolerance and insulin resistance." (PMID 32655492, 2020). "Previous studies have shown the loss of leptin action in obese cases, indicating leptin resistance and many conditions have been reported exhibiting mutation in leptin receptor leading to obesity due to some other reason in mice and rats." (PMID 32272767, 2020). "As African Americans have a higher prevalence of both obesity and diabetes, we aimed to assess the association of leptin with type 2 diabetes in the Jackson Heart Study, the largest ongoing cohort of African Americans." (PMID 32131811, 2020). "Leptin is the most well-known and highly studied adipokine and disruptions in proper leptin function result in severe obesity through hyperphagia (overeating) and associated metabolic disorders." (PMID 33270666, 2020). "The aim of this study was to evaluate the effect of dietary-induced weight loss on the daily rhythms of leptin and ghrelin and its influence on the daily variability of the appetite sensations of patients with obesity." (PMID 32230732, 2020). "Human and rodent studies have shown that obesity is associated with higher plasma leptin concentrations." (PMID 33105762, 2020). "The leptin-deficient (ob/ob) or (Lepob/Lepob) mouse model develops hyperphagia, obesity, transient hyperglycaemia, high serum insulin, elevated numbers of pancreatic beta cells, lowered LH, GH in the serum but higher hypophyseal Prl protein content." (PMID 32183843, 2020). "Leptin-deficient and leptin-resistant mice manifest obesity, insulin resistance, and left ventricular hypertrophy (LVH); however, LVH’s mechanisms are not fully understood." (PMID 32346034, 2020). "Congenital leptin deficiency is a form of monogenic obesity and caused by mutations in the gene encoding leptin (LEP, known as the ob gene in the mouse)." (PMID 32655492, 2020). "Leptin deficiency (Lepob; commonly called ob or ob/ob) causes spontaneous obesity in mice, resulting in ob/ob mice reaching a bodyweight thrice that of normal mice." (PMID 32164196, 2020). "Genetic knockdown of Ucp2 can prevent diet induced obesity and restore insulin sensitivity in leptin deficient ob/ob mice." (PMID 33240218, 2020).
Obesity (continued). "We assessed the association of leptin and adiponectin with incident type 2 diabetes (T2D), their interactions with sex and obesity status, and mediation by insulin resistance." (PMID 32131811, 2020). "Despite leptin’s long-term effect of limiting food intake, a paradoxical hallmark of obesity is hyperleptinemia." (PMID 32244756, 2020). "Several studies further ascribe obesity-associated inflammation in the hypothalamus to alternations in leptin signaling at its cognate receptor (LepR)." (PMID 32152264, 2020). "High level of circulating leptin enhanced the risk of ASCVD in overweight or obesity through promoting endothelial dysfunction and the expression of profibrotic markers in the heart." (PMID 32802124, 2020). "Mutations in genes linked to the leptin-melanocortin signaling in the hypothalamus are associated with monogenic obesity." (PMID 32153512, 2020). "These SNPs have also been shown to be strongly associated with obesity in a Chinese population when both were simultaneously present with a LEP 3’flanking region polymorphism." (PMID 32069871, 2020). "Some of the genes that code for the leptin–melanocortin pathway proteins are associated with monogenetic or polygenic obesity." (PMID 32982666, 2020). "Unlike monogenic leptin-deficient ob/ob and db/db mouse models, the FATZO mouse model is a polygenic inheritance of predisposition to obesity and diabetes, with an intact leptin pathway, thereby making it more translatable to the human disease." (PMID 33374435, 2020). "Leptin has also been shown to be associated with obesity, a form of chronic inflammation, considered in the etiopathogenesis of intestinal inflammation." (PMID 33110098, 2020). "Insulin and leptin are important molecules which are implicated in metabolic homeostasis, and their interactions are of clear interest because of the link with obesity and diabetes." (PMID 32839413, 2020). "For instance, sexual hormones play an indirect role to the dysregulation of adipokines during the development of obesity and diabetes, possibly resulting in a stronger correlation between elevated leptin levels and diabetes risk in males versus females." (PMID 31947955, 2020). "Adipokines play a leading role in connecting obesity and systemic inflammation: adiponectin and leptin are associated with obesity and are both lower in adult males in respect to females with the same body mass index." (PMID 32102344, 2020). "On the other hand, obese people have increased leptin concentrations indicating obesity-linked leptin-resistance." (PMID 31055727, 2020). "It has been well established that hypothalamic inflammation is a primary cause of leptin resistance, which is deeply associated with obesity pathogenesis." (PMID 32560726, 2020). "An important result in terms of 1H-NMR glycoproteins and obesity is the considerable association found between GlycA and the leptin/adiponectin ratio, which suggests that GlycA is a marker of adipose tissue-associated low-grade inflammation." (PMID 32012794, 2020). "Our study provides a rationale for the anti-obesity effect and intestinal protection effect of AC in leptin-deficient obese mice." (PMID 32164196, 2020). "We also found that high leptin levels were strongly associated with the risk of obesity and insulin resistance." (PMID 33299020, 2020). "Of note, a number of negative regulators of JAK2, including SOCS3, PTP1B, RPTPe, and TCPTP, have been reported to promote obesity, supporting the notion that JAK2 inhibitory molecules increase risk for leptin resistance, obesity, and metabolic disease." (PMID 32251290, 2020). "Leptin is involved in the development of obesity and leptin deficiency (due to mutations in the ob gene) can be causal for obesity." (PMID 32789683, 2020). "Common obesity is associated with leptin resistance, a major aspect of the pathophysiology of this disease." (PMID 32528252, 2020). "Inflammation linked to obesity plays an important role in altering, centrally, the action of leptin." (PMID 32545890, 2020).